SKP2 (S-phase kinase associated protein 2)
Diseases named in the same sentence as SKP2 in open-access papers (continued):
Sharing a sentence is not in itself a finding about the gene and the disease.
cancer (continued). "It is highly worth noting that, although this study focuses on the ubiquitination of a single protein (SKP2) in a single cancer type, it has implications for other proteins in other cancer types, since ubiquitination and proteasomal degradation is a universal cellular process." (PMID 35169199, 2022). "Therefore, many experts and scholars are using Skp2 as a target for cancer treatment to explore more cancer treatment methods." (PMID 35845132, 2022). "In addition, SKP2 expression was negatively correlated with MLN4924 IC50 values in almost all cancer types." (PMID 35685435, 2022). "Besides, we detected the mRNA level and protein expression of SKP2 in various cancer cell lines in several cancer types." (PMID 35685435, 2022). "Using publicly available TCGA (The Cancer Genome Atlas) data, we show that SKP2 copy number losses (i.e., shallow deletions) are frequent in many common cancer types and correspond with reduced mRNA expression and worse progression-free survival in CRC patients." (PMID 36496990, 2022). "The comprehensive pan-cancer analysis suggested that inhibition of Skp2 with MLN4924 might be an effective therapeutic strategy for attenuating tumor cell proliferation in YAP-driven cancers." (PMID 35685435, 2022). "SKP2 is an F-box protein and E3 ubiquitin ligase that is involved in many key cellular processes such as cell cycle regulation, apoptosis, senescence, and the regulation of cancer stem cells." (PMID 36293387, 2022). "Since SKP2 degrades FOXO1 upon methylation by G9a, targeting SKP2 activity may enhance FOXO1 activity despite increased G9a activity in cancers." (PMID 35740522, 2022). "In human cancer, p27 levels are frequently reduced by SKP2 overexpression." (PMID 35597806, 2022). "All data above suggested that the elevation of SKP2 expression could increase cancer cell sensitivity towards MLN4924 in pan-cancer." (PMID 35685435, 2022). "Cancers can also occur with enhanced degradation of forkhead box O1 (FOXO1) by Skp2." (PMID 36499442, 2022). "Similarly, SKP2 targets Cyclin E1, whose aberrant accumulation leads to cell cycle and apoptotic defects that also promote cancer development and progression." (PMID 36496990, 2022). "SKP2 triggers non-proteolytic K63-linked ubiquitination, which is crucial for cancer initiation and progression by positively regulating cancer cell survival and glycolysis." (PMID 35874839, 2022). "Skp2 is overexpressed in various cancers and promotes tumor occurrence and malignancy." (PMID 36499442, 2022). "Strikingly, SKP2 was positively correlated with the expression of MKI67 in almost all cancer types." (PMID 35685435, 2022). "Hence, we propose to assess SKP2 and p27 expression levels to stratify cancer patients considered for CHK1‐inhibitor treatment." (PMID 35673965, 2022). "Though the precise mechanism underlying Skp2 deficiency-increased FBW7 and Mcl-1 interaction remains unclear, the oncoprotein Skp2 is still an attractive anti-cancer target." (PMID 35301297, 2022). "As a result, a positive feedback loop may exist between YAP and SKP2, possibly regulating the sensitivity of cancer cells to ferroptosis." (PMID 36147464, 2022). "It suggested that high SKP2 expression may increase the responsiveness towards MLN4924 in multiple cancer types." (PMID 35685435, 2022). "Moreover, we provided evidence that higher SKP2 expression increases the sensitivity of cancer cell lines towards MLN4924." (PMID 35685435, 2022). "This suggests that the downregulation of SKP2 may inhibit cancer growth, migration, and invasion in AIPC cells." (PMID 34366863, 2021). "Lymphocyte-specific protein tyrosine kinase (LCK) phosphorylates Tyrosine-342 of FOXP3 and upregulates its expression resulting in decreased Matrix metalloproteinase 9 (MMP9), S-phase kinase-associated protein 2 (SKP2), and Vascular endothelial growth factor A (VEGF-A) levels in cancer cells." (PMID 33614551, 2021).
cancer (continued). "Depletion of Skp2-induced apoptosis of drug resistant cancer cells and could be a promising method to overcome drug resistance." (PMID 34068643, 2021). "In addition, overexpression of SKP2 correlates with the reduction of TRUSS in human cancers, suggesting an interplay of MYC Ub ligases in tightly controlling MYC stability during the cell cycle." (PMID 34178666, 2021). "Furthermore, abnormal protein-expression levels of Skp2 and p27Kip1 have been detected in many malignancies; both proteins play important roles in the pathogenesis and development of malignant tumors, and their expression levels also impact patient prognosis." (PMID 33664437, 2021). "NUCKS1 and SKP2 are overexpressed in most TCGA datasets, including many shared cancer types." (PMID 34845229, 2021). "Our observations showed that, once inside the cancer cells, Artemisinin-mediated blockage of FoxM1 trans-activation results in downregulation of major transcriptional targets of FoxM1, such as Plk1, cyclinB1, Skp2 and Aurora B kinase." (PMID 34900697, 2021). "The cellular thermal sift assay showed the Skp2 is more stable in cells treated with the compound at a temperature range of 57 to 68 °C, which indicated compound SYK-031 could specifically target Skp2 in cancer cells." (PMID 34702937, 2021). "Therefore, inhibition of SKP2 promotes the deterioration of cancer by targeting promotion of p21 and p27 and by cell senescence." (PMID 34075107, 2021). "Another caveat of our study is the lack of cell fractionation analysis in in vitro experiments (i.e., Skp2 inhibition by siRNA, compound 25, and MLN4924) and the provision of only indirect evidence of Skp2 and Slug colocalization in cancer tissues and their coexpression in in vitro models." (PMID 33799604, 2021). "Linichlorin A and gentian violet also inhibits the interaction between Skp2–Cks1 and p27, thus inhibiting the ubiquitination and degradation of p27 in HeLa cells, which indicates a potential strategy for restoring p27 levels in human cancers." (PMID 34068643, 2021). "Therefore, inhibition of Skp2 function by small-molecule compounds targeting Skp2-Cks1 interaction is emerging as a promising and novel anti-cancer strategy." (PMID 34702937, 2021). "Here, we hypothesized that 20(S)-Rh2E2 may also interrupt cancer cell energy production and cell cycle progression via the Skp2 autoinduction loop." (PMID 32796841, 2020). "Thus, MLN4924 is a potential new IVT therapy for RB that harnesses the exquisite SKP2-dependency of this pediatric cancer." (PMID 32123578, 2020). "Other possible advantages of SKP2 as a therapeutic target in cancer include the potential for selective targeting compared with the use of other signaling inhibitors with broader activities or higher toxicity, such as the proteasomal inhibitor bortezomib or the CDK4/6 inhibitors." (PMID 31772299, 2020). "Researches about the SKP2 signaling suggest that SKP2 targeting may be a very attractive approach to treat human cancers." (PMID 32856866, 2020). "Several other FBXL family members have also been implicated in cancer, but unlike Skp2, are thought to act as tumour suppressors." (PMID 33234069, 2020).
cancer (continued). "Indeed, overexpression of SKP2 is found in a variety of human cancers promoting progression, invasion and metastasis, while deficiency inhibits these processes." (PMID 32683422, 2020). "SKP2 has oncogenic roles and is overexpressed in various types of cancers." (PMID 32826949, 2020). "Among them, the CDK inhibitor p27 is likely to be the most relevant cancer-related SKP2 substrate." (PMID 32560247, 2020). "A growing body of literature strongly implies that SKP2 is an oncoprotein in human cancers." (PMID 30999935, 2019). "Thus, we showed that Skp2 is important for maintaining the cancer stem-like phenotype of DU 145 mesenchymal cells in term of the CD44+CD24− phenotype." (PMID 30952903, 2019). "Skp2 positively regulates cancer stem cell populations and CSC self-renewal ability in human cancers, which suggests that targeting Skp2 could restrict cancer stem cells and cancer progression." (PMID 30999935, 2019). "The F-box protein SKP2 plays an oncogenic role in human cancers." (PMID 30341246, 2019). "Furthermore, SKP2 enhances DNA damage response and promotes DNA double-strand break repair pathways in cancer cells." (PMID 30341246, 2019). "Thus, we showed that the nuclear expression of Skp2 is significantly increased in patients with a high Gleason score (≥7) whose cancer cells exhibit characteristics of the mesenchymal state." (PMID 30952903, 2019). "Furthermore, we observed that Skp2 downregulation led to the decrease in subpopulation of CD44+CD24− cancer stem-like cells." (PMID 30952903, 2019). "SKP2 overexpression is frequently found in human cancer and plays a critical role in tumorigenesis." (PMID 31357665, 2019). "Thus, AMPK acts through Skp2 S256 phosphorylation and Akt activation to maintain cancer cell survival under hypoxia and glucose deprivation." (PMID 30413706, 2018). "More mechanistic knowledge into the Skp2 overexpression in various cancers holds great therapeutic potential as inhibiting p27-Skp2 interactions may reverse its malignant phenotype." (PMID 29479529, 2018). "There are also reports that Skp2 plays a role in cancer metastasis." (PMID 30250282, 2018). "Inhibition of Skp2 has been demonstrated to potentially restrict cancer progression." (PMID 30176860, 2018). "Due to its significant role in cancer development and progression, we wondered whether Skp2 expression was also related to KIF4A in this study." (PMID 29396392, 2018). "Skp2 is an F-box protein and E3 ubiquitin ligase that participates in many key cellular processes such as cell cycle regulation, senescence, apoptosis, and regulation of cancer stem cells." (PMID 30250282, 2018). "We first tested whether AMPK acts through the Skp2/Akt axis to regulate cancer cell survival under diverse metabolic stresses." (PMID 30413706, 2018). "SZL-P1-41 also inhibits Skp2-dependent cell growth in cancer cell lines in vitro." (PMID 29415439, 2018). "A further putative mechanism at the basis of CDKN1C down-regulation might be related to an increased rate of protein degradation, mainly due to the Skp2 overexpression, as frequently observed in human cancers." (PMID 29614816, 2018). "Evidence shows that SKP2 had a high expression level in several human tumors and could promote the proliferation and metastasis of cancer cells." (PMID 28178195, 2017). "Numerous cancers display poor prognosis if harboring overexpressed SKP2 protein." (PMID 28665315, 2017).
cancer (continued). "Targeting Skp2 could induce cancer cell apoptosis and suppress tumorigenesis, while inhibition of Skp2-mediated p27 and E-cadherin degradation leads to cell cycle blockage and migration inhibition." (PMID 28036296, 2017). "Additionally, we found that DEK and Skp2 regulation were involved in the mechanisms of these anti-cancer effects." (PMID 28578385, 2017). "Moreover, RhoA GTPase is crucial in cancer metastasis, and Skp2 induces RhoA transcription and consequently promotes cell migration, invasion, and cancer metastasis." (PMID 28157698, 2017). "Finally, we describe how the MYC/CDK2/p27/SKP2 axis impacts on tumor development and discuss possible ways to interfere therapeutically with this system to improve cancer treatment." (PMID 28665315, 2017). "SKP2 also plays an important role in regulating the cell cycle by controlling the expression of other target proteins, including p21, p57, p130, c-Myc, and E2F1, which are associated with the initiation, development, treatment, and prognosis of cancer." (PMID 28178195, 2017). "Collectively, these studies suggest that targeting Skp2 is a promising strategy for cancer therapy." (PMID 28036296, 2017). "Of 169 cases with immunohistochemical staining, 88 cases showed p-Skp2 staining in carcinoma cells." (PMID 28446188, 2017). "Upregulation of Skp2 has been observed in various malignant tumors." (PMID 27258250, 2016). "It has been shown that SKP2 is overexpressed in many cancers." (PMID 26956626, 2016). "We hypothesized that Rh2E2 may interrupt cancer cell energy production and cell cycle progression via the Skp2 autoinduction loop." (PMID 26799418, 2016). "Indeed, the increase of Skp2 content has been reported as an independent marker of cancer malignity and aggressiveness." (PMID 26682002, 2016). "Due to the oncogenic function of Skp2 in tumorigenesis, inactivation of Skp2 could be helpful for treating human cancers." (PMID 27582552, 2016). "Overexpression of skp2 could enhance cancer cell viability in the presence of Rh2E2, suggesting that Rh2E2-enhanced cytotoxicity was offset by skp2." (PMID 26799418, 2016). "Thus, the discovery that HDACIs downregulate Skp2 levels has important pharmacological implications in cancer development and prognosis." (PMID 26682002, 2016). "Since SKP2 and CCNA2 are known to be implicated in the pathogenesis of various cancers as oncogenes, the effects of each TIA1 protein isoform on the SKP2 and CCNA2 protein levels were investigated using cells transiently expressing each isoform via retroviral infection." (PMID 26958940, 2016). "Skp2 functions as an oncoprotein in a variety of human cancers." (PMID 27582552, 2016). "As several studies have shown that some E3 ligases, including Hdm2 and the F-box protein Skp2, are highly expressed in a number of human cancers, and also present in serum, it is possible that these E3 ligases can be further developed as useful cancer biomarkers." (PMID 25599194, 2015). "Future studies should determine whether expression levels of FZR1 or its proteolytic targets such as SKP2 provide prognostic markers for the response of cancer cells to CDK4/6 inhibitor treatment." (PMID 25562820, 2015). "Skp2-dependent decrease in p27 levels was observed in cancer cells, leading to poor prognosis." (PMID 25886174, 2015). "It is also required to determine whether curcumin exerts its anti-cancer function through inhibiting Skp2 expression in glioam mouse models in vivo." (PMID 26046466, 2015). "Further investigation of this novel Cullin1-mediated Skp2 degradation pathway may present new opportunity for targeting Skp2 in prevention and treatment of cancer." (PMID 26497688, 2015).
cancer (continued). "For example, Skp2 targeting suppresses tumorigenesis and induces apoptosis of cancer cells." (PMID 26474281, 2015). "Skp2 is an oncoprotein that is overexpressed in many cancers." (PMID 25886174, 2015). "However, the mechanisms underlying the deregulation of H3K4me3 by JARID1B and the relevance with SKP2 in cancers are poorly understood." (PMID 25596733, 2015). "It has been reported that Skp2 could be inhibited by caffeic acid phenethyl ester and curcumin in cancer cell lines." (PMID 26046466, 2015). "The discovery of a novel degradation pathway for Skp2 induced by statins opens up the exiting possibility that this pathway may be targeted in cancer therapy." (PMID 25605247, 2015). "Skp2 plays a central role in cell cycle regulation, cellular senescence, apoptosis, metabolism, metastasis, and cancer stem cells by ubiquitinating a wide range of substrates, including p27, ORC1, Cdt1, KMT2A/MLL1 and others, for targeted degradation by the proteasome." (PMID 26497688, 2015). "This reciprocal regulation between DAB2IP and Skp2 protein represents a unique homeostatic balance between tumor suppressor and oncoprotein in normal prostate epithelia, which is apparently altered in cancer cells." (PMID 25115390, 2014). "Although STAT3 activity has been shown to influence SKP2 expression and subsequently p27 levels in several cancer cells, it had remained whether STAT3-mediated SKP2/p27 regulation exhibited an important role in the direction of senescence program." (PMID 25412315, 2014). "Notably, the Skp2 inhibitor exhibited potent antitumor activities in multiple animal models and cooperated with chemotherapeutic agents to reduce cancer cell survival." (PMID 25471937, 2014). "Finally, the E3 ligase, Skp2, has been shown to be overexpressed in numerous human cancers and plays a critical role in cell-cycle progression, senescence, metabolism, cancer progression, and metastasis." (PMID 25471937, 2014). "Experiments using either xenograft or genetic mouse models illustrated that deficiency in Skp2, TRAF6 or TRAF4 results in suppression of cancer development in vivo, pointing to the critical role of distinct E3 ubiquitin ligases in Akt-mediated biological functions and cancer progression." (PMID 25309720, 2014). "The formation of the E-cadherin/AhR/Skp2 complex and ubiquitination of E-cadherin induced by kynurenine is also detectable in A549 cells, indicating a general mechanism of kynurenine-induced proteolysis of E-cadherin in different cancer cells." (PMID 25060643, 2014). "Skp2 is an important cell cycle regulator, which is widely studied in various cancer types." (PMID 25015320, 2014). "Our study not only interprets the predictive role of Skp2 in the poor prognosis of NPC patients, but also reveals that Skp2 regulates the NPC cancer stem cell maintenance, which shed lights on the target therapy and early diagnosis of NPC in clinical application." (PMID 25015320, 2014). "In addition, abundant studies showed the high expression of SKP2 was one characteristic of human tumor growth, and SKP2 was not only used as an independent prognosis of cancer patients, but also as a new target of antitumor drugs and gene therapy." (PMID 24455688, 2013). "Skp2 is a promising target for restricting cancer stem cell and cancer progression, it’s overexpression is frequently observed in human cancer and it may, therefore, act as an oncogene." (PMID 24265759, 2013). "Recently, a growing body of research data has shown that Skp2 plays an oncogenic role and its expression may contribute to the development and progression of human cancers." (PMID 23939428, 2013).